PRMT5 (protein arginine methyltransferase 5)
Description:
Arginine methyltransferase that can both catalyze the formation of omega-N monomethylarginine (MMA) and symmetrical dimethylarginine (sDMA), with a preference for the formation of MMA. Specifically mediates the symmetrical dimethylation of arginine residues in the small nuclear ribonucleoproteins Sm D1 (SNRPD1) and Sm D3 (SNRPD3); such methylation being required for the assembly and biogenesis of snRNP core particles. Methylates SUPT5H and may regulate its transcriptional elongation properties. May methylate the N-terminal region of MBD2. Mono- and dimethylates arginine residues of myelin basic protein (MBP) in vitro. May play a role in cytokine-activated transduction pathways. Negatively regulates cyclin E1 promoter activity and cellular proliferation. Methylates histone H2A and H4 'Arg-3' during germ cell development (By similarity). Methylates histone H3 'Arg-8', which may repress transcription (By similarity). Methylates the Piwi proteins (PIWIL1, PIWIL2 and PIWIL4), methylation of Piwi proteins being required for the interaction with Tudor domain-containing proteins and subsequent localization to the meiotic nuage (By similarity). Methylates RPS10. Attenuates EGF signaling through the MAPK1/MAPK3 pathway acting at 2 levels. First, monomethylates EGFR; this enhances EGFR 'Tyr-1197' phosphorylation and PTPN6 recruitment, eventually leading to reduced SOS1 phosphorylation. Second, methylates RAF1 and probably BRAF, hence destabilizing these 2 signaling proteins and reducing their catalytic activity. Required for induction of E-selectin and VCAM-1, on the endothelial cells surface at sites of inflammation. Methylates HOXA9. Methylates and regulates SRGAP2 which is involved in cell migration and differentiation. Acts as a transcriptional corepressor in CRY1-mediated repression of the core circadian component PER1 by regulating the H4R3 dimethylation at the PER1 promoter (By similarity). Methylates GM130/GOLGA2, regulating Golgi ribbon formation. Methylates H4R3 in genes involved in glioblastomagenesis in a CHTOP- and/or TET1-dependent manner. Symmetrically methylates POLR2A, a modification that allows the recruitment to POLR2A of proteins including SMN1/SMN2 and SETX. This is required for resolving RNA-DNA hybrids created by RNA polymerase II, that form R-loop in transcription terminal regions, an important step in proper transcription termination. Along with LYAR, binds the promoter of gamma-globin HBG1/HBG2 and represses its expression. Symmetrically methylates NCL. Involved in spliceosome maturation and mRNA splicing in prophase I spermatocytes through the catalysis of the symmetrical arginine dimethylation of SNRPB (small nuclear ribonucleoprotein-associated protein) and the interaction with tudor domain-containing protein TDRD6 (By similarity).
Synonyms: SKB1Hs; HRMT1L5; IBP72; JBP1; SKB1; HSL7
Tractability: Small molecule: a drug acting on it is in phase 2 or 3 trials; a structure with a bound ligand is known; a high-quality ligand is known. PROTAC: ubiquitination databases record sites on it; its protein half-life has been measured; a small molecule that binds it is known.
Target class: Epigenetic regulator; Protein arginine methyltransferase; Writer; Protein methyltransferase
Chemical probes: DS-437, EPZ015666 (high quality), GSK591 (high quality), LLY-283 (high quality), MRK-990 (high quality), MS023 (high quality)
Gene: Protein-coding gene on chromosome 14 (22,920,525 to 22,929,458, reverse strand). Ensembl gene ENSG00000100462.
Subcellular location: Cytoplasm; Nucleus; Chromosome; Golgi apparatus
Subcellular location (Human Protein Atlas): Cytosol; Nucleoplasm
Pathways (Reactome):
Chromatin organization: RMTs methylate histone arginines
Metabolism of RNA: snRNP Assembly
Gene Ontology:
Molecular function: histone H4R3 methyltransferase activity; identical protein binding; methyl-CpG binding; methyltransferase activity; protein binding; protein heterodimerization activity; protein-arginine N-methyltransferase activity; protein-arginine omega-N symmetric methyltransferase activity; ribonucleoprotein complex binding; E-box binding; histone H3 methyltransferase activity; histone methyltransferase activity; transcription corepressor activity; protein-containing complex binding
Biological process: chromatin remodeling; DNA-templated transcription termination; endothelial cell activation; Golgi ribbon formation; negative regulation of cGAS/STING signaling pathway; peptidyl-arginine N-methylation; positive regulation of adenylate cyclase-inhibiting dopamine receptor signaling pathway; spliceosomal snRNP assembly; circadian regulation of gene expression; positive regulation of mRNA splicing, via spliceosome; positive regulation of rRNA processing; regulation of DNA-templated transcription; regulation of mitotic nuclear division; cellular response to growth factor stimulus; liver regeneration; negative regulation of cell differentiation; negative regulation of DNA-templated transcription; negative regulation of gene expression via chromosomal CpG island methylation; positive regulation of oligodendrocyte differentiation; regulation of ERK1 and ERK2 cascade; regulation of gene expression
Cellular component: chromatin; chromosome; cytoplasm; cytosol; Golgi apparatus; histone methyltransferase complex; methylosome; nucleoplasm; nucleus; protein-containing complex
Genetic constraint (gnomAD): Loss-of-function variants: 15 observed, 85.01 expected, observed/expected ratio (o/e) 0.18, 90% interval 0.12 to 0.27. The upper end of that interval is the gene's LOEUF score, 0.27, which puts it in group 1 of 6, group 1 being the genes least tolerant of losing a copy. Missense variants: 480 observed, 838.04 expected, observed/expected ratio (o/e) 0.57, 90% interval 0.53 to 0.62. Synonymous variants: 276 observed, 308.87 expected, observed/expected ratio (o/e) 0.89, 90% interval 0.81 to 0.99.
Homologues: Orthologues: dog PRMT5 (99% identical), guinea pig PRMT5 (99% identical), rabbit PRMT5 (98% identical), mouse Prmt5 (98% identical), rat Prmt5 (97% identical), macaque PRMT5 (96% identical), chimpanzee PRMT5 (95% identical), pig PRMT5 (93% identical), zebrafish prmt5 (78% identical), tropical clawed frog prmt5 (76% identical), Drosophila melanogaster csul (37% identical), Caenorhabditis elegans prmt-5 (35% identical).
Diseases named in the same sentence as PRMT5 in open-access papers:
PRMT5 is named in the same sentence as 250 diseases in open-access papers, as found by Europe PMC text mining. Sharing a sentence is not in itself a finding about the gene and the disease. The quoted sentences say what the papers report.
breast carcinoma (114 papers, 2012 to 2026). "We have previously identified the arginine methyltransferase PRMT5, a protein associated with breast cancer progression, metastatic disease, and poor prognosis, as an important regulator of BCSC function and survival." (PMID 39695328, 2025). "In CDK4/6 inhibitor-resistant ER+/RB-deficient breast cancer, PRMT5 inhibition represents a viable therapeutic strategy, leading to the dissociation of FUS from RNA polymerase II and subsequently suppressing the DNA synthesis." (PMID 39678513, 2024). "Collectively, these data support PRMT5 as a therapeutically actionable vulnerability to overcome resistance to CDK4/6 inhibitors in ER+/RB-deficient breast cancer." (PMID 38480701, 2024). "In this study using a genome-wide CRISPR screen, we identified PRMT5 as a molecular dependency in ER+/RB-deficient breast cancer." (PMID 38480701, 2024). "Recent studies have linked elevated PRMT5 levels to a variety of human disorders, particularly cancers, including lung cancer, breast cancer, leukemia, lymphoma, gastric cancer, and colorectal cancer." (PMID 39255317, 2024). "Since RB1 loss-of-function alterations confer resistance to CDK4/6i in ER+ metastatic breast cancer patients, a genome-wide CRISPR screen identified protein arginine methyltransferase 5 (PRMT5) as a vulnerability in ER+/RB1-deficient breast cancer cells." (PMID 38672640, 2024). "Amplification of CLNS1A was linked to worse outcomes in luminal breast-cancer tumors, possibly by helping to recruit proteins to the PRMT5 complex." (PMID 38132437, 2023). "In this study using a genome-wide CRISPR screen with ER+/RB-deficient cells, we identified PRMT5 as a novel dependency in breast cancer." (PMID 37502925, 2023). "Collectively, these results suggest that PRMT5 is an actionable molecular vulnerability in ER+/RB-deficient breast cancer cells." (PMID 37502925, 2023). "Taken together, these data support PRMT5 as a therapeutically actionable vulnerability to overcome resistance to CDK4/6 inhibitors in ER+/RB-deficient breast cancer." (PMID 37502925, 2023). "Treatment with the PRMT5i inhibitor pemrametostat and fulvestrant synergistically inhibited growth of ER+/RB-deficient patient-derived xenografts, suggesting dual ER and PRMT5 blockade as a novel therapeutic strategy to treat ER+/RB-deficient breast cancer." (PMID 37502925, 2023). "Next, we asked if inhibition of the methyltransferase activity of PRMT5 was required to block growth of ER+/RB-deficient breast cancer cells." (PMID 37502925, 2023). "Inhibition of PRMT5 blocked the G1-to-S cell cycle transition in ER+/RBKO breast cancer cells and other cancer cells with natural loss-of-function alterations of RB1." (PMID 37502925, 2023). "Among these, epigenetic modifiers that were previously implicated in breast cancer cell fitness, such as PRMT5, HDAC3, NPM1 were depleted in MDA-MB-231 cells serving as positive controls." (PMID 35973998, 2022). "Previous studies have shown that high MEP50 and high PRMT5 mRNA levels are associated with worse prognosis in the whole breast cancer population." (PMID 36230689, 2022). "Kaplan–Meier survival analysis revealed that lower expression of PRMT5 was associated with improved survival of patients with breast cancer, lung cancer, liver cancer, and gastric cancer." (PMID 33953349, 2021). "Of note, we did not observe an apparent association between PI3KCA mutations and sensitivity to PRMT5 inhibitor in these breast cancer cells we examined." (PMID 34103528, 2021). "From a clinical perspective, high PRMT5 has been associated with a poor prognosis in patients with breast cancer, hepatocellular carcinoma, lung cancer, ovarian, and gastric cancer." (PMID 34685445, 2021). "Conversely, other studies report nuclear localization of PRMT5 to be associated with reduced cell growth and better patient outcomes in breast cancer and prostate cancer where nuclear exclusion signals have been identified." (PMID 33989303, 2021).
breast carcinoma (continued). "In line with its influence on proliferation and self-renewal of embryonic and adult stem cells, PRMT5 has recently been implicated in the regulation of breast cancer stem cell (BCSC) function." (PMID 30613353, 2018). "Nuclear PRMT5 expression has been found to be directly associated with invasive colorectal carcinoma and highly proliferative breast cancer." (PMID 28107179, 2017). "Moreover, studies have indicated that tamoxifen induces PRMT5 translocation to the nucleus in tamoxifen-sensitive cells, with higher nuclear PRMT5 levels associated with improved survival in luminal breast cancer cells." (PMID 38791992, 2024). "Collectively, our data suggest that dual blockade of ER and PRMT5 can effectively suppress tumor growth of ER+/RB-deficient breast cancer, thus providing the basis for testing this therapeutic combination in patients with this refractory breast cancer genotype." (PMID 38480701, 2024). "Collectively, our data suggest that dual blockade of ER and PRMT5 can effectively suppress tumor growth of ER+/RB-deficient breast cancer, thus providing the basis to testing this novel therapeutic combination in patients with this refractory breast cancer subtype." (PMID 37502925, 2023). "Moreover, elevated PRMT5 expression is associated with poor prognosis and chemotherapeutic resistance in breast cancer patients." (PMID 37400460, 2023). "In addition, PRMT5 overexpression has been associated with poor prognosis in gastric, lung, and breast cancers." (PMID 32932854, 2020). "Given that PRMT5 is known to promote these stem cell traits, and that high levels are associated with a poor prognosis for breast cancer patients, we rationalised that PRMT5 activity could be a major driving force in the maintenance of BCSCs." (PMID 29876520, 2018). "Indeed, we find that PRMT5 upregulation tightly associated with an increase in KLF4 levels is a common feature in mammary cancer." (PMID 26420673, 2015). "In breast cancer, PRMT5 modulates the sensitivity of breast cancer cells to doxorubicin by regulating OCT4/A, KLF4 and C-MYC." (PMID 41513606, 2026). "In lung cancer, EPZ015666 impairs radioresistance, while in breast cancer, inhibiting PRMT5 suppresses the growth of paclitaxel-resistant cancer cells." (PMID 41513606, 2026). "PRMT5 is also phosphorylated by liver kinase B1, suppressing its pro-tumoral enzymatic activity in breast cancer cells." (PMID 40791817, 2025). "To extend our observations to clinical samples, we checked the PRMT5 transcript and protein levels along with the PRMT5-mediated modifications H4R3me2s and H3R8me2s in patient-derived breast cancer cell line BC8322, subjected to hypoxia." (PMID 41150697, 2025). "In other words, 21% of all splicing events affected by PRMT5 inhibition in patient-derived glioblastoma cells are also misregulated in breast cancer cells shifted to homocysteine medium." (PMID 39862967, 2025). "In breast cancer, tamoxifen treatment induces PRMT5 nuclear translocation, enabling methylation of ERα." (PMID 40919714, 2025). "The role PRMT5 plays in the development of breast cancer, lung cancer, prostate cancer, gastric cancer, pancreatic cancer, and melanoma is multifold." (PMID 40869229, 2025). "In glioblastoma and breast cancer models, PRMT5 inhibitors (e.g., EPZ015666, pemrametostat) have been shown to overcome resistance to mTOR inhibitors (e.g., PP242) and CDK4/6 inhibitors (e.g., abemaciclib, palbociclib, ribociclib)." (PMID 41204384, 2025). "Next, we performed IHC-F to detect PRMT5 expression in tumor sections derived from breast cancer patients." (PMID 41150697, 2025). "In this study, we initially observed that among all PRMTs, PRMT5 was upregulated in breast cancer patients as well as in breast cancer cell lines." (PMID 41150697, 2025).
breast carcinoma (continued). "Next, to validate PRMT5 expression under hypoxia, we performed quantitative RT-PCR (qRT-PCR) and immunoblotting to understand PRMT5 gene and protein expression in two breast cancer cell lines MCF7 and MDA-MB-231 subjected to hypoxia." (PMID 41150697, 2025). "PRMT5 is overexpressed in breast cancer patients, and it results in the activation of the Wnt/beta-catenin proliferative signaling pathway, leading to enhanced expression of c-myc and CYCLIN D1 and SURVIVIN." (PMID 40869229, 2025). "The study found that PRMT5 inhibition blocks the G1/S transition in breast cancer cells, arresting cell growth." (PMID 40650785, 2025). "We observed a significant positive correlation (R = 0.42) between the gene expression of PRMT5 and hypoxia markers indicating that hypoxia regulates PRMT5 gene expression in human breast cancers." (PMID 41150697, 2025). "For instance, a PRMT5/EGFR dual inhibitor based on the 1-phenyl-tetrahydro-β-carboline scaffold exhibited potent antitumor activity in breast cancer models." (PMID 41204384, 2025). "Previous studies in breast cancer cells have shown that PRMT5 activity supports DNA repair by promoting BRCA1 mRNA stability through m6A demethylation pathways." (PMID 40919714, 2025). "Ongoing trials are evaluating additional PRMT inhibitors, including GSK3368715 (targeting PRMT1) and CMP5 (targeting PRMT5), in patients with advanced malignancies, including breast cancer." (PMID 40791817, 2025). "In breast cancer, PRMT5 regulates OCT4/A, KLF4, FOXP1, and c-Myc expression to promote CSC proliferation, self-renewal, and resistance." (PMID 41204384, 2025). "In breast cancer, PRMT5 promotes tumor growth by methylating key substrates: it stabilizes KLF4 by inhibiting its ubiquitylation, leading to Bax downregulation and oncogene upregulation, and it methylates PDCD4, abolishing its tumor-suppressive function." (PMID 41204384, 2025). "In this study, we observed hypoxia-induced upregulation of PRMT5 via the CTCF in human breast cancer cells." (PMID 41150697, 2025). "In the future, it will be important to examine the correlation between nuclear PRMT5 and RORα in human breast cancer tissue." (PMID 38791992, 2024). "By regulating KEAP1, NRF2, and HMOX1 expression levels, PRMT5 promotes resistance to immunotherapy-induced ferroptosis in breast cancer." (PMID 39201539, 2024). "Through a genome-wide CRISPR screen, we identify protein arginine methyltransferase 5 (PRMT5) as a molecular vulnerability in ER+/RB1-knockout breast cancer cells." (PMID 38480701, 2024). "To investigate this, we initially examined the effect of PRMT5 on PD-L1 expression in breast cancer MDA-MB-231 and MCF7 cell lines." (PMID 39366935, 2024). "In breast cancer, particularly, the expression level of PRMT5 is markedly elevated when compared to that in normal breast tissue." (PMID 39614393, 2024). "PRMT5 predominantly localizes in the cytoplasm in aggressive TNBCs, while it tends to localize in the nucleus of certain luminal breast cancer cells and normal mammary epithelial cells." (PMID 38791992, 2024). "Here, the authors identify a vulnerability of ER + /RB1- breast cancer on PRMT5 and via dual blockade of ER and PRMT5 therapeutically target this in patient-derived xenograft models." (PMID 38480701, 2024). "In summary, our findings underscore the significance of the circGSK3β-miR-338-3p-PRMT5-H3K4me3 axis in promoting breast cancer progression and immune evasion." (PMID 39366935, 2024). "Targeted inhibition of PRMT5 has demonstrated effective suppression of the growth, proliferation, migration, and invasion of breast cancer cells." (PMID 39614393, 2024).